HPSE (heparanase)
Diseases named in the same sentence as HPSE in open-access papers (continued):
Sharing a sentence is not in itself a finding about the gene and the disease.
cancer (continued). "For many years, an intensive effort was dedicated to revealing the role of heparanase in human pathologies, mainly in cancer, leading to the appreciation that heparanase is a target for the development of anti-cancer therapeutics." (PMID 37491420, 2023). "The role of HPSE in the development of cancers is mainly due to its degradation activity of HS, which facilitates metastasis dissemination and cell invasion." (PMID 37508554, 2023). "Studies performed before cloning of the HPSE gene contributed immensely to our understanding of key features in the biology of the enzyme, its mode of action, and involvement in cancer metastasis and inflammation." (PMID 37547889, 2023). "The dysregulation of heparanase-1 expression in cancer has been extensively documented over the two past decades and forms a key hallmark of cancer." (PMID 36680276, 2023). "Given the well-documented anti-cancer effects of heparanase inhibition, our findings attest this enzyme to be a unique target in cancer therapy due to its dual action." (PMID 36979689, 2023). "Given that heparanase is a well-recognized target for inhibition of cancer progression and inflammation, our findings further strengthen this notion by broadening the multitasking molecular function of the heparanase gene and protein." (PMID 36980232, 2023). "For example, pixatimod (PG545) and PI-88 are HPSE inhibitors developed for use in cancer that, like heparin, have anticoagulant activity." (PMID 37915090, 2023). "These facts imply that heparanase inhibitors will have only minimal side effects in clinics and make heparanase-1 an important target for anti-cancer therapy." (PMID 36680276, 2023). "SDCs and heparanase (an enzyme that cleaves heparan sulfate) have been studied as potential targets in cancer treatment." (PMID 37759706, 2023). "While the role of HPSE in cancer, where it promotes tumour metastasis, is well described, its involvement in neuroinflammatory diseases such as MS is less well understood." (PMID 37915090, 2023). "Cancer cells can express procoagulant factors, including tissue factor, cancer procoagulant, and heparanase, which are important for activation of the coagulation cascade." (PMID 35719003, 2022). "Heparanase (HPSE) is the principal enzyme responsible for extracellular heparan sulfate catabolism and is markedly up-regulated in aggressive cancers." (PMID 35881786, 2022). "Since the cloning and expression of HPSE in 1999, emerging evidence highlighted the involvement of HPSE in cancer progression, inflammation and angiogenesis." (PMID 36157032, 2022). "HPSE overexpression drives aggressive cancer growth and metastasis, leading to correspondingly worsened clinical outcomes." (PMID 35881786, 2022). "Compelling evidence indicates that the heparanase (HPSE) gene has multiple functions in cancer, however, its role in BRAF V600E-mutant CRC remains elusive." (PMID 36130926, 2022). "We highlight novel emerging data on immunoglobulin-containing and proline-rich receptor-1, heparanase and thrombospondin 1 in autophagy and cancer." (PMID 34982945, 2022). "Numerous studies have shown conclusively that heparanase plays a critical role in the advancement of cancer by degrading HSPGs, which in turn promotes neovascularization processes that support the invasion of metastatic cells." (PMID 36144768, 2022). "Heparin and its derivatives, as well as other sulfated polysaccharides like fucoidan, have heparanase inhibitory activity, which enables them to block cancer cell invasion or prevent metastasis in in vitro experiments." (PMID 36144768, 2022). "We show that these HS-configured pseudodisaccharides are nanomolar, irreversible HPSE inhibitors in vitro and markedly reduce cancer aggression in in cellulo and in vivo cancer models." (PMID 35881786, 2022). "Clinical trials testing heparanase inhibitors as an anti-cancer therapy show early signs of efficacy, further underscoring the clinical importance of this enzyme." (PMID 34982945, 2022).
cancer (continued). "The isatin sulfonamide derivatives showed an ability to depress the action of the survival mechanism of Bcl-2, inhibiting angiogenesis, and further hindering cancer invasion through inhibition of uPA and heparanase expression." (PMID 35327524, 2022). "Heparanase was documented to enhance sEV secretion, and alter sEV cargos and functions in several human cancer cell lines." (PMID 35558506, 2022). "Pharmacological HPSE inhibition effectively ameliorates aggression and metastasis across a wide range of cancer types." (PMID 35881786, 2022). "The heparanase produced by cancer cells has also been suggested to cleave HS of the basement membrane (BM), which is necessary for them to infiltrate the BM of blood vessels during metastasis." (PMID 36340029, 2022). "Compelling evidence suggest that HPSE is a multifaceted protein participating in multiple biological processes, some excellent reviews are available pertaining to the engagement of HPSE in cancer progression, inflammation and angiogenesis." (PMID 36157032, 2022). "HPSE also plays an important role in several disease settings including cancer metastasis, inflammation, and diabetes." (PMID 36291066, 2022). "As expected, we found that the expression of HPSE was lower in these cancer tissues than in the paired adjacent normal tissues and was significantly associated with survival." (PMID 35840985, 2022). "Heparanase has been demonstrated to be secreted by cancer cells to promote their invasion and metastasis by degrading heparan sulfate in the extracellular matrix." (PMID 36144836, 2022). "HPSE expression was lower in ESCC tissues than para-carcinoma tissues, consistent with our genetic analysis." (PMID 35840985, 2022). "A number of other growth factors—basic fibroblast growth factor (bFGF), FGF23, and platelet-derived growth factor—have also been shown to increase heparanase expression in cancer cells." (PMID 34681753, 2021). "Several preclinical models have promoted the anti-cancer potential of HPSE inhibition and clinical trials have been carried out for the HPSE inhibitors PI-88 (muparfostat), PG545 (pixatimod), SST0001 (roneparstat) and M-402 (necuparanib)." (PMID 33809973, 2021). "Because of these implications, HPSE inhibition constitutes an attractive pharmacological target for the development of cancer therapies." (PMID 33809973, 2021). "Various drugs targeting HPSE activity have already been developed and some of them are currently assessed in clinical trials to reduce cancer progression, either as adjuvant or as novel therapy." (PMID 34677445, 2021). "It is known that the metastatic ability of cancer cells is associated with the degradation of the ECM and increased heparanase expression." (PMID 33917849, 2021). "In recent years, several heparanase inhibitors have been synthesized and are currently being studied in clinical trials as potential cancer treatments." (PMID 34112915, 2021). "The expression of heparanase is regulated and known to be increased in several different types of cancer." (PMID 33561383, 2021). "While several HPSE inhibitors are currently under clinical trials as novel anti-cancer therapeutics, it is tempting to study the effect of these inhibitors on HSV-1 infection in an in vivo model of infection." (PMID 34578329, 2021). "Expression of heparanase is also dysregulated in many disease settings, such as its upregulation in cancer." (PMID 34681753, 2021). "Many studies have demonstrated that the prognosis of cancer patients is closely related to heparanase expression." (PMID 34220326, 2021). "Several previous reports suggested that SNPs of HPSE are accompanying with different types of cancers, such as hematological malignancies, gastric cancer, and ovarian carcinoma." (PMID 33411145, 2021). "In this study, we analyzed the correlation between HPSE expression and prognosis in cancer patients, using multiple databases (Oncomine, TIMER, PrognoScan, GEPIA, Kaplan–Meier plotter, miner v4.1, DAVID)." (PMID 34461608, 2021).
cancer (continued). "Heparanase expression was shown to be upregulated in all cancer types, including sarcomas, carcinomas, and hematological neoplasms." (PMID 33800172, 2021). "So, targeting HPSE and modulating its activity is a very valuable strategy to overcome several cancer features and improve disease outcome." (PMID 33494442, 2021). "Among HS modifying enzymes, HPSE is definitely one of the most investigated as a cancer drug target." (PMID 33494442, 2021). "The observation that heparanase can confer chemotherapeutic resistance in cancer cells led to the discovery that the chemotherapies bortezomib, carfilzomib, and doxorubicin can induce the upregulation of heparanase in vitro." (PMID 34681753, 2021). "Heparanase is therefore considered to be a valid drug target, and heparanase inhibitors are being evaluated clinically in cancer patients." (PMID 33959505, 2021). "Heparanase is normally expressed at extremely low levels, but upregulated under pathological conditions, e.g., cancer and inflammation, as a reactant protein." (PMID 33971986, 2021). "In this research, we analyzed HPSE expression and the role played in the prognosis of cancer patients." (PMID 34461608, 2021). "Intensive research effort devoted in the last two decades to explore the significance of heparanase in cancer led to the recognition that heparanase is a valid drug target." (PMID 33959505, 2021). "These compounds showed not only good enzyme inhibitory potencies, but also promising biological activities, being able to block cancer cell invasiveness and to affect gene transcription as expected from effective heparanase inhibitors." (PMID 32907434, 2020). "Heparanase was also found to induce tissue factor expression in vascular endothelial and cancer cells and to induce dissociation of tissue factor pathway inhibitor from the vascular surface." (PMID 32121387, 2020). "In this study, inhibition of heparanase activity significantly reduced the ability of cancer cells to migrate and infiltrate." (PMID 32471161, 2020). "Heparanase is a validated target in cancer therapy and a potential target for several inflammatory pathologies." (PMID 32907434, 2020). "Heparanase overexpression and secretion by cancer cells results in degradation of endogenous heparin and hypercoagulability." (PMID 32121387, 2020). "Translocation of HPSE to the nucleus has been shown to promote differentiation in human and mouse cancer cell lines." (PMID 33256730, 2020). "Heparanase, an enzyme implicated in the degradation of HSPG is found upregulated in many cancers such as in advanced-stage RCC." (PMID 32411604, 2020). "HPSE regulates the classic and emerging hallmarks of cancer as well as all enabling characteristics, as discussed in the following sections." (PMID 33256730, 2020). "SOD3 protects the integrity of HS by reducing heparanase expression and by preventing ROS-mediated HS degradation, thus reducing cancer cell proliferation and invasion." (PMID 33250894, 2020). "Heparanase promotes cancer growth, metastasis, and angiogenesis by inducing the degradation of heparan sulfate (HS), a sulfated glycosaminoglycan." (PMID 33250894, 2020). "Another enzyme playing an important role in accessing the blood circulation is heparanase, which cleaves HS polysaccharides located in the basement membrane and on the cancer cell surface, leading to increased invasive behavior of cancers." (PMID 32984308, 2020). "Inhibiting the expression of heparanase by siRNA suppressed the proliferative activity of cancer cells strongly, and cytotoxicity was observed." (PMID 32471161, 2020). "With the current trend towards the discovery and clinical trials of novel HPSE inhibitors, this contradictory role of HPSE in cancer must be addressed." (PMID 33256730, 2020). "Upregulation of HPSE is detected in a wide range of human cancers by immunohistochemistry, in situ hybridization, real‐time PCR analyses and is shown to correlate with metastatic potentials." (PMID 32869952, 2020).
cancer (continued). "In anticancer therapy heparanase is already a validated target, given the extensive studies confirming its involvement in cancer cell growth and spreading, angiogenesis and metastasis." (PMID 32907434, 2020). "Previous studies have demonstrated the association between heparanase (HPSE, OMIM 604,724) single‐nucleotide polymorphism (SNP) and cancer risk in several cancers." (PMID 32869952, 2020). "Heparanase is physiologically expressed in platelets and the placenta and is pathologically overexpressed in most malignant tumors." (PMID 32121387, 2020). "The subsequent sections will discuss the mechanisms by which HPSE regulates each of the hallmarks of cancer, which define it as a key component within the TME." (PMID 33256730, 2020). "This review will focus on the possibility to control HS turnover by acting upon heparanase, at both extracellular and intracellular levels, a strategy that can be applied to many conditions, from inflammation to cancer and neurodegeneration." (PMID 31963505, 2020). "Heparanase expression was elevated in high-grade compared to low-grade carcinoma samples (34.7% vs. 23.4%, respectively)." (PMID 32471161, 2020). "It is likely that platelet heparanase contributes to platelet-endothelial cell adhesion and the hyper-thrombotic conditions seen in cancer patients via another mechanism." (PMID 31850210, 2019). "The first reports of heparanase inhibitors in an anti-cancer or anti-metastatic activity, stemmed from the use of heparin and low molecular weight heparins (LMWHs)." (PMID 32010611, 2019). "Despite the complex pro/anti-tumorigenic axis of heparanase, exploiting heparanase has shown promise in leukocyte-based anti-cancer therapies." (PMID 31110966, 2019). "Despite these issues, we believe heparanase remains a useful therapeutic target in the battle against cancer metastasis." (PMID 31850210, 2019). "An emerging area of significant clinical interest is at the intersection of heparanase, leukocytes, and cancer." (PMID 31110966, 2019). "In this article, we look at heparanase from the viewpoint of heparanase as a drug target, and ask why has the translation from preclinical studies to successful clinical trials of drug candidates targeting heparanase in cancer been so difficult?" (PMID 31850210, 2019). "The plasma obtained from patients with different types of cancer was able to elicit an upregulation of HPSE, HPSE2 and Syn-1 mRNA expression." (PMID 30922347, 2019). "Choosing the appropriate anti-cancer therapy will lie in finding the balance in particular cancer settings between inhibiting pro-tumorigenic heparanase and promoting its anti-tumorigenic effects." (PMID 31110966, 2019). "The robust expression of heparanase across multiple cancer types and cell types makes it a useful target to manipulate and utilize its anti-cancer properties." (PMID 31110966, 2019). "Given that minor side-effects can be tolerated in an anti-cancer drug, it is fair to say that heparanase scores quite positively on this point." (PMID 31850210, 2019). "The ability of heparanase to regulate these processes also makes it a key player in several pathological settings such as inflammatory disease and cancer." (PMID 31110966, 2019). "Despite these advances, further investigation is required to fully understand the role of heparanase in leukocyte function during cancer progression." (PMID 31110966, 2019). "When cancer cells were exposed to exogenous heparanase or the expression of heparanase was promoted, the release of TEXs increased dramatically." (PMID 31438991, 2019). "The ability to design and synthesize HS mimicking structures that eliminate anti-coagulation activity and target heparanase has more recently been facilitated with use of computational modeling to predict the anti-cancer/anti-metastatic potential." (PMID 32010611, 2019). "In a proteomic study aimed at identify aspirin-bound proteins in cancer cells, heparanase has been detected as a target." (PMID 31362364, 2019).